IGFBP3 (insulin like growth factor binding protein 3)
Diseases named in the same sentence as IGFBP3 in open-access papers (continued):
Sharing a sentence is not in itself a finding about the gene and the disease.
colorectal cancer (continued). "IGF-2 and IGFBP-3, on the other hand, exhibited statistically significant, positive associations with colorectal cancer risk when cases were confined to those diagnosed within a relatively short time period after enrolment (within 8 years)." (PMID 11742490, 2001). "This is the first study to investigate the associations of IGF-1, IGF-2 and IGFBP-3 concentrations with the risk of colorectal cancer in prospectively collected blood samples from an Oriental population." (PMID 11742490, 2001). "In addition, another serologic analysis based on a genome-wide association study revealed that the level of IGFBP3 predicted an increasing risk of colorectal cancer (OR = 1.12)." (PMID 36660244, 2023). "Further research is recommended to investigate if circulating IGF1 and IGFBP3 levels can be used to identify people at high risk of colorectal cancer and to investigate potential lifestyle or pharmaceutical ways to lower IGF1 bioactivity as a risk reduction strategy." (PMID 34858769, 2021). "Further research is recommended to investigate if circulating IGF1 and IGFBP3 levels can be used to identify people at high risk of colorectal cancer and to explore potential lifestyle or pharmaceutical ways to lower IGF1 bioactivity as a risk reduction strategy targeting high-risk individuals." (PMID 34858769, 2021). "If large sample studies could explore the association between IGFBP3 polymorphisms and colorectal cancer, IGFBP3 may provide an example of a gene whose polymorphic variation is relevant to the pharmacogenomics of cancer prevention." (PMID 23527244, 2013). "Results of meta-analysis for IGFBP3 A-202C/Gly32Ala polymorphism and colorectal cancer." (PMID 23527244, 2013). "In conclusion, if confirmed in other studies, the results from this study suggest that improving vitamin D status may help lower risk of colorectal cancer associated with higher IGF-1/IGFBP3 ratio or C-peptide levels." (PMID 22216097, 2011). "The results from this study suggest that improving vitamin D status may help lower risk of colorectal cancer associated with higher IGF-1/IGFBP-3 ratio or C-peptide levels." (PMID 22216097, 2011). "Furthermore, an association between IGFBP-3 and cancer risk was confirmed in colorectal cancer." (PMID 37510722, 2023). "We can speculate that because colorectal cancer is associated with chronic inflammation in the gut, inflammatory cytokines, and growth factors released in response to chronic inflammation may influence the expression and secretion of IGFBP-3." (PMID 37764678, 2023). "However, from a public health point of view, if confirmed these findings would provide a relatively easy way to reduce risk of colorectal cancer among those with high IGF-1/IGFBP-3 ratio or high C-peptide levels as vitamin D status is an easily modifiable risk factor." (PMID 22216097, 2011). "Among the upregulated target genes, we highlighted six that are closely linked to colorectal cancer: LGALS9, GLUT1, IGFBP3, CDK4, DUSP1, and HIF1A." (PMID 41411347, 2025). "Increased expression of IGFBP3 in RCC (and also in lung and colorectal cancer) was associated with inferior overall survival, while IGFBP5 expression had no apparent impact on prognosis in RCC." (PMID 39516665, 2024). "HOXD10 was identified as a biological correlate of tumor suppressor DNA and an inducer of miRNA-7 and insulin-like growth factor binding protein 3 in colorectal cancer." (PMID 37812190, 2023). "In colorectal cancer, IGFBP-3 levels were noted to be higher when the disease was stable, and they decreased in cancer progression." (PMID 37510722, 2023). "Bioinformatics analysis of TCGA data shows IGFBP-3 mRNA levels are significantly lower in breast, liver and cervical cancers, while slightly increased in colorectal cancer (CRC) compared to normal tissue." (PMID 36430216, 2022).
colorectal cancer (continued). "Inconsistently, a study revealed that miR-197 facilitated invasion of tumor cells by regulating insulin-like growth factor-binding protein 3 (IGFBP3) in colorectal cancer." (PMID 35130798, 2022). "Previous studies have shown that IGFBP3 plays a crucial role in the tumor progression in various cancers, such as colorectal cancer, squamous esophageal cancer, nasopharyngeal carcinoma, glioma, and lung adenocarcinoma." (PMID 34094948, 2021). "Restoration of HOXD10 activates the expressions of miR-7 and IGFBP3 and results in an inhibited phenotype biologically, suggesting its potential therapeutic relevance in colorectal cancer (CRC)." (PMID 34790580, 2021). "We observed in our study the highest IGFBP-1, IGFBP-2 and IGFBP-3 mRNA expression in Dukes’ stage D colorectal cancer cells, having the lowest level IGFBP-6." (PMID 34290976, 2021). "In this work, we show that TGF‐β produced by colorectal cancer cells activates pericytes that in turn promote their tumorigenic properties through the release of soluble factors, including IGFBP‐3, with a prominent role in cancer cell migration and invasion." (PMID 32767843, 2020). "The present study aimed to investigate the clinical significance of serum IGFBP‐3 in colorectal cancer (CRC)." (PMID 31218761, 2019). "High circulating levels of IGF-1 and low levels of IGFBP-3 (a major IGFBP that accounts for ~75% of IGF-1 bound) have been shown to be associated with an increased risk of several types of cancers, including colorectal cancer." (PMID 18976499, 2008). "Our data thus suggest that circulating IGF-2 and IGFBP-3 can serve as early indicators of impending colorectal cancer." (PMID 11742490, 2001). "This study explored the relationships of serum insulin-like growth factors, IGF-I and IGF-II, and their binding proteins (IGFBP)-2 and IGFBP-3, with key clinicopathological parameters in 92 patients with colorectal cancer (cases)." (PMID 11044360, 2000). "IGFBP3, an inhibitor of insulin-like growth factors, regulates cell survival and apoptosis, and its upregulation may help colorectal cancer cells resist cell death." (PMID 41411347, 2025). "The association of IGFBP-3 with a positive family history of colorectal cancer has not been a focus of significant research." (PMID 37764678, 2023). "Previous research has found that the downregulated IGFBP3 might serve as a candidate marker for colorectal cancer diagnosis, which consistent with our findings." (PMID 37397026, 2023). "We next characterized the anti-tumor IGFBP-3/IGFBP-3R signaling axis in colorectal cancer cells." (PMID 36430216, 2022). "The correlation between AC068491.1.1 and IGFBP3 differed between normal and colorectal cancer tumor samples; in normal samples, AC068491.1.1 and IGFBP3 were negatively correlated (r = –0.49, P = 0.038), while in colorectal cancer samples they were positively correlated (r = 0.69, P = 0.001)." (PMID 28152521, 2017). "Interestingly, AC068491.1.1, a lncRNA that was upregulated 3.0-fold and with FDR < 0.001, was functionally coordinated with IGFBP3, which is known to be involved in colorectal cancer and liver metastasis." (PMID 28152521, 2017). "By contrast, higher plasma IGFBP-3 levels were protective against colorectal cancer." (PMID 23304125, 2012). "Our findings also suggest that among those with low plasma 25(OH)D levels, having either high IGF-1/IGFBP-3 ratio or high C-peptide levels increased risk, but being high in both did not further increase colorectal cancer risk appreciably." (PMID 22216097, 2011).
colorectal cancer (continued). "IGF-1, IGF-2 and IGFBP-3 were measured in the serum of 135 men who developed colorectal cancer over 12 years of follow-up and 661 control subjects drawn from the cohort, who were matched to the index cases by neighbourhood of residence, age, and year and month of sample collection." (PMID 11742490, 2001). "Translated to a cancer context, targeting of oncogenic IGFBP-3 by miR-19a-3p might contribute to the observation in colorectal cancer that lncRNA LINC00342, which is highly expressed and acts as ceRNA to sponge miR-19a-3p, promotes CRC cell growth and invasion." (PMID 35597813, 2022). "We may not have detected an association between IGFBP3 A-202C polymorphism and colorectal cancer for several reasons." (PMID 23527244, 2013). "In conclusion, this meta-analysis suggests that IGFBP3 A-202C and Gly32Ala polymorphisms may not be associated with colorectal cancer development." (PMID 23527244, 2013). "Therefore, as in colorectal cancer, IGFBP-3 may mediate the oncogenic effect of miR-197." (PMID 35597813, 2022). "Meanwhile, miR-197 can inhibit the expression of IGFBP3 through binding with its 3′-UTR, hence enhancing cell migratory potential and invasion of colorectal cancer cells." (PMID 33768092, 2021). "It is interesting to note that subjects with a positive family history of colorectal cancer had greater circulating levels of IGFBP-3 at the end of the trial than subjects without a family history." (PMID 37764678, 2023). "Besides, aberrant expressions of miR-204-5p, miR-197, and miR-155-5p participate in the pathogenesis of papillary thyroid carcinoma, colorectal cancer, and non-small lung cancer through affecting expressions of IGFBP5, IGFBP3, and IGFBP1, respectively." (PMID 33768092, 2021). "In addition, our data revealed that IGFBP3 promoter methylation serves as an independent prognostic biomarker in stage II and III colorectal cancer patients." (PMID 25127039, 2014). "IGF-1 has been detected in colorectal cancers and is a strong stimulator of colorectal cancer cell proliferation in vitro, but GH treatment usually results in increases in both IGF-I and IGFBP-3." (PMID 23761782, 2013). "A similar relationship between serum C-peptide levels (a marker for insulin production) and colorectal cancer risk was reported in the Physicians' Health Study, and this association was independent of IGF-1 and IGFBP-3 levels." (PMID 23304125, 2012). "Elevated plasma IGFBP-3 has been associated with reduced risk of colorectal cancer (CRC), but the role of tissue IGFBP-3 is not well defined." (PMID 18498652, 2008). "For example, B-MYB accelerates the cell cycle in colorectal cancer cells 47 by upregulating the E2F2/ERK/AKT signaling pathway, and suppressing IGFBP3 expression to promote proliferation and metastasis in non-small cell lung cancer." (PMID 40303285, 2025). "No studies have yet clarified IGFBP-3 expression on IHC in invasive breast cancers in comparison with DCIS, although there has been a limited review of colorectal carcinomas and normal colonic mucosa[B9]." (PMID 15642160, 2005).
Obesity (54 papers, 2012 to 2026). Accumulation of substantial excess body fat. "Other studies have shown that children who are overweight or obese have higher serum IGFBP-3 levels and that IGFBP-3 concentrations are linked to several cardiovascular risk factors, including obesity and insulin levels." (PMID 40538800, 2025). "Nevertheless, the current study results configure the potential clinical utility of MEG3/miR-27a/IGF1/IGFBP3 axis, especially miR-27a in screening and early diagnosis of obesity-associated CRC." (PMID 38704452, 2024). "The results also accentuate circulating MEG3/miR-27a/IGF1/IGFBP3 as valuable markers of the early detection of obesity-related CRC, with miR-27a is associated with its risk." (PMID 38704452, 2024). "Obese patients have lower IGF-1 during adulthood and obesity has a weaker association with IGFBP-3 compared with IGF-1." (PMID 37510722, 2023). "Other hypertension-associated genes impacted by obesity included Podxl and Ebf1 upregulated in lung art ECs, Nbeal1 and Tbx3 upregulated in heart art ECs and Igfbp3 with reduced expression in heart, kidney and brain art ECs." (PMID 36400935, 2022). "We found that gene expression of GHR, IGF-1 and IGFBP-3 was compromised in AT of children with overweight/obesity and was associated with parameters of adipocyte function such as adipocyte hypertrophy and increased fasting insulin levels." (PMID 36384443, 2022). "Positive associations between obesity and IGFBP-3 have been reported across race and menopausal groups." (PMID 26352264, 2015). "Obesity was also associated with increased expressions of angiogenesis-related proteins, in particular, angiogenin, endoglin, endostatin, endothelin-1, IGFBP-3, leptin, MMP-3, PAI-1, TIMP-4, CXCL16, platelet factor 4, DPPIV and coagulation factor III." (PMID 22748184, 2012). "Notably, miR-27a and IGFBP3 were excellent discriminators, with miR-27a recorded the highest diagnostic accuracy for obesity-related CRC." (PMID 38704452, 2024). "The high Vitamin D status correlated with the serological upregulation of IGFBP-2 in males and IGFBP-3 in females with obesity and may constitute surrogate markers of risk reduction of cardiometabolic disease." (PMID 30287811, 2018). "This diminished response is accompanied by a lower serum IGFBP‐3 response, highlighting a coordinated (dys) regulation of both IGF‐1 and IGFBP‐3 responses to exercise in individuals with obesity." (PMID 40574473, 2025). "Contradictory findings have also been published regarding IGFBP-3 levels in obesity, since higher IGFBP-3 was shown in obese individuals, but other papers did not verify these findings." (PMID 41226444, 2025). "Because the production of both IGF‐1 and IGFBP‐3 occurs primarily in the liver, our findings suggest the presence of shared hepatic mechanisms that inhibit the secretion of both IGF‐1 and IGFBP‐3 in response to exercise in individuals with obesity." (PMID 40574473, 2025). "Higher values of phosphorus and IGFBP-3 were observed in children with overweight/obesity, as compared to children with normal weight, (p=0.042) and (p=0.042), respectively." (PMID 38634087, 2024). "Here, although IGFBP3 seemed to be a predictor of obesity-CRC risk in the univariate analysis, only a marginal association of IGFBP3 (P = 0.055) was inferred from the multivariate analysis." (PMID 38704452, 2024). "Particularly, the negative correlation of serum IGFBP3 with LN metastasis in obese CRC patients implicates IGFBP3 in the pathogenesis and progression of obesity-related CRC." (PMID 38704452, 2024). "The higher phosphorus and IGFBP-3 concentrations observed in children of 8–12 years with overweight/obesity indicate a higher growth rate in these children." (PMID 38634087, 2024). "Our findings accentuate circulating MEG3/miR-27a/IGF1/IGFBP3, especially miR-27a as valuable markers for the early detection of obesity-related CRC." (PMID 38704452, 2024).
Obesity (continued). "In conclusion, children with overweight/obesity showed higher phosphorus and IGFBP-3 concentrations, as compared to children with normal weight." (PMID 38634087, 2024). "In our study, differences only reached statistical significance in phosphorus and IGFBP-3 concentrations, which were higher in children with overweight/obesity." (PMID 38634087, 2024). "The group of children with overweight/obesity showed significantly higher phosphorus and IGFBP-3 concentrations, as compared to children with normal weight (p<0.042 and p<0.042, respectively)." (PMID 38634087, 2024). "Serum GHBP levels were increased in children with overweight/obesity throughout childhood, while for IGF-1 levels and the IGF-1/IGFBP-3 molar ratio obesity-related elevations were detectable until early puberty." (PMID 36384443, 2022). "We observed that gene expression of GHR and IGF-1 in adipocytes and expression of IGFBP-3 in SVF cells was decreased in children with overweight/obesity compared to lean children." (PMID 36384443, 2022). "Total IGF-1 and IGFBP3 concentrations in subjects with obesity are mildly elevated, as we observed in this study, but free IGF-1 levels are increased." (PMID 35412268, 2022). "We furthermore found a relation of reduced IGFBP-3 expression in AT cells with obesity and with increased AT inflammation, which fits to previously proposed anti-inflammatory and pro-apoptotic effects." (PMID 36384443, 2022). "Studies have shown that short stature children were prone to complications from nutritional metabolic disorders such as malnutrition and obesity, which were associated with IGF-1 and IGFBP-3." (PMID 35180848, 2022). "Means of IGF-1 and IGFBP3 in the undernutrition group were significantly lower than means in the eutrophic and obesity groups." (PMID 34684579, 2021). "As for IGFBP-3, this protein inhibits adipocyte differentiation and impacts the peroxisome proliferator-activated receptor-gamma (PPARγ) system, suggesting a role for IGFBP-3 in the pathogenesis of obesity and IR." (PMID 32911852, 2020). "In conclusion, IGFBP-2 and IGFBP-3 were found to correlate with vitamin D status in males and female adults with obesity, respectively." (PMID 30287811, 2018). "Our functional studies by EMSA suggested that the differential expression pattern of IGFBP-3 in obesity is regulated by higher expression of the VDR in HIR-MO and LIR-MO, respectively, in adipose tissue." (PMID 29112142, 2017). "High serum levels of insulin-like growth factor-1 (IGF-1) and low levels of insulin-like growth factor binding protein-3 (IGFBP-3) are associated with obesity, and obesity is associated with NALFD development." (PMID 28335515, 2017). "Our results show a novel role of the VD system in the regulation and activation of IGFBP-3 in visceral adipose tissue (VAT) of patients with MO, as a new and alternative mechanism proposed in the insulin signaling associated with obesity." (PMID 29112142, 2017). "This study investigated the role of endogenous IGFBP-3 on the development of obesity and subsequently on breast tumor growth." (PMID 27448965, 2016). "This suggests that the tumor growth-suppressive environment created by low host IGFBP-3 can, in part, be negated with development of obesity." (PMID 27448965, 2016). "Levels of IGF-1, IGFBP-3, and several adipokines related to obesity and cancer were examined in the serum of the mice 10 weeks after the last AOM injection." (PMID 24732966, 2014). "Taken together, these in vitro data provide convincing evidence that IGFBP-3 negates obesity-induced NF-κB activity in adipocytes and HAECs." (PMID 23383064, 2013). "In this study we show that IGFBP-3 proteolysis was significantly increased in overweight as well as obesity groups compared to normal controls by both western blotting and protease activity assay." (PMID 23383064, 2013). "Girls with overweight/obesity showed significantly higher IGFBP-3 concentrations, p=0.026." (PMID 38634087, 2024).